LILRB2 (leukocyte immunoglobulin like receptor B2)
Diseases named in the same sentence as LILRB2 in open-access papers (continued):
Sharing a sentence is not in itself a finding about the gene and the disease.
malaria (4 papers, 2018 to 2025). Malaria is a serious and sometimes fatal disease caused by a parasite that commonly infects a certain type of mosquito which feeds on humans. "The inverse relation between LILRB2 gene expression and IL-8 plasma levels in UM patients also suggests that LILRB2 expression may be involved in the limitation of malaria severity since this chemokine was found to be a risk factor for death during CM." (PMID 38835780, 2024). "Elucidating the interactions between RIFINs and LILRB1/LILRB2 not only sheds light on the immune evasion strategies of P. falciparum but also provide novel insights for the development of malaria treatments and vaccines." (PMID 40860159, 2025). "It would be thus interesting to test whether inhibition of LILRB2 and maybe LILRB1 and Tim3 could help restore the phagocytosis capacity of monocytes during the first days of CM and limit malaria severity." (PMID 38835780, 2024). "Higher expression of LILRB1 and LILRB2 on intermediate and non-classical monocytes at 18 and 24 months during active malaria." (PMID 35911674, 2022). "Additionally, infants born to mothers with placental malaria showed LILRB2 overexpression on non-classical monocytes, highlighting its potential role in mediating malaria-induced immune tolerance." (PMID 40860159, 2025). "The concomitant presence of IL-10 and a higher expression of LILRB1 and LILRB2 on non-classical monocytes suggests a down regulation of the cells involved in inflammatory mechanisms and therefore a potentially decreased ability to protect the infants from malaria." (PMID 35911674, 2022). "Infants born to women with PM had a higher risk of developing symptomatic malaria than those born to women without PM (IRR=1.53, p=0.040), and such infants displayed a lower frequency of non-classical monocytes (OR=0.74, p=0.01) that overexpressed LILRB2 (OR=1.36, p=0.002)." (PMID 35911674, 2022).
psoriatic arthritis (4 papers, 2014 to 2024). Joint inflammation associated with psoriasis. "Reduced expression or impaired function of LILRB1 and LILRB2 have been associated with inflammatory autoimmune conditions such as rheumatoid or psoriatic arthritis and systemic lupus erythematosus." (PMID 39691709, 2024). "Hence, modulating LILRB2 expression on human monocytes may reverse psoriatic arthritis–associated effects." (PMID 35076022, 2022). "Conversely, LILRB2 is markedly downregulated on monocytes from patients with psoriatic arthritis and may contribute to disease progression." (PMID 35076022, 2022).
rheumatoid arthritis (4 papers, 2021 to 2025). A chronic, systemic autoimmune disorder characterized by inflammation in the synovial membranes and articular surfaces. "Interestingly, traits like platelet-to-lymphocyte ratio, sphingomyelin, cathepsin B, and LILRB2 protein levels have been positively associated with rheumatoid arthritis." (PMID 39175752, 2024). "Rheumatoid arthritis patients abundantly express LILRA2, LILRA3, LILRA5, and LILRB2, with the presence of LILRA2, LILRA5, and LILRB2 significantly correlating with disease activity." (PMID 34737739, 2021). "LILRB2, LILRB3 and LILRA2 were highly upregulated in synovial tissues from rheumatoid arthritis (RA) patients." (PMID 34594332, 2021).
Sepsis (4 papers, 2014 to 2021). Sepsis is defined as life-threatening organ dysfunction caused by a dysregulated host response to infection. "In this regard, transcriptomic analysis showed a significant downregulation of LILRB2 in the very early phase of sepsis that is associated with increased risk of death." (PMID 34594332, 2021). "Increasing evidence has indicated an interplay between LILRB2 modulation and the host response to sepsis initiated by exacerbated inflammation and followed by immunosuppressive responses." (PMID 34594332, 2021). "Another study demonstrated an increased expression of LILRB2 in monocytes during severe sepsis." (PMID 34594332, 2021). "LILRB2 up-regulation upon stimulation was dysregulated under sepsis conditions." (PMID 34276685, 2021). "This failure of LILRB2 upregulation on neutrophils may correspond to the immunoparalysis state observed in sepsis patients." (PMID 34594332, 2021).
chronic lymphocytic leukemia (3 papers, 2014 to 2024). "LILRB2 and LILRB4 were demonstrated to be specific biomarkers of chronic lymphocytic leukemia (CLL) and show consistent expression patterns between the two receptors." (PMID 39696628, 2024).
lung adenocarcinoma (3 papers, 2020 to 2025). A carcinoma that arises from the lung and is characterized by the presence of malignant glandular epithelial cells. "LILRB2 may be a suitable target, as increased LILRB2 expression in patients with lung adenocarcinoma correlates with reduced T cell infiltration in the tumor milieu, and is predictive of worsened clinical outcomes." (PMID 35076022, 2022).
multiple sclerosis (3 papers, 2014 to 2024). A progressive autoimmune disorder affecting the central nervous system resulting in demyelination. "However, we also identified traits with less clear connections to JIA, including platelet-to-lymphocyte ratio, sphingomyelin levels, cathepsin B levels, LILRB2 protein levels, multiple sclerosis, and giant cell arteritis." (PMID 39175752, 2024). "A recent study investigating the mode of action of glatiramer acetate (Copaxone), a peptide-based drug licensed in the late 1990s, used to treat patients with the relapsing-remitting form of multiple sclerosis that ameliorates autoimmunity, identified LILRB2 and LILRB3 as potential ligands." (PMID 32870822, 2020).
prostate carcinoma (3 papers, 2022 to 2025). A carcinoma that arises from epithelial cells of the prostate gland. "LILRB2 is expressed on several types of cancers, including colon, breast, pancreas, lung, hepatocellular and prostate cancers and leukaemia." (PMID 38022598, 2023). "In prostate cancer, LILRB2 together with LILRB3 and LILRB5 expression have been associated with reduced recurrence-free survival in intermediate but not high-risk patients." (PMID 38022598, 2023).
atherosclerosis (2 papers, 2021 to 2025). A disease characterized by the build-up of fatty material and calcium deposition in the arterial wall resulting in partial or complete occlusion of the arterial lumen. "Although a number of reports have indicated LILRB2 expression in human macrophages, its exact role with respect to molecular mechanisms underlying peripheral atherosclerosis remain elusive." (PMID 35321392, 2021). "This study aimed to examine the regulatory role of leukocyte immunoglobulin‐like receptor B2 (LILRB2) in macrophage extracellular trap (MET) formation in foam macrophages in atherosclerosis (AS)." (PMID 41235141, 2025). "Our research examined how leukocyte immunoglobulin‐like receptor B2 (LILRB2) impacts macrophage extracellular trap (MET) formation in foam macrophages within atherosclerosis (AS)." (PMID 41235141, 2025). "The importance of LILRB2 in human atherosclerosis is increasingly evident with reports linking the LILRB2 ligand ANGPTL2 to cardiovascular disease." (PMID 35321392, 2021).
liver fibrosis (2 papers, 2023 to 2024). "On the other hand, another study suggested that ANGPTL8 is a proinflammatory factor that accelerates liver fibrosis through its receptor LILRB2 and downstream ERK signaling pathways in the context of high fat diet-induced inflammatory activity." (PMID 37634084, 2024). "Since HSCs also contribute to liver fibrosis, we also investigated the role of the ANGPTL8/LILRB2 axis in HSC-MDM crosstalk if exists." (PMID 37481670, 2023).
myocardial infarction (2 papers, 2021 to 2023). Gross necrosis of the myocardium, as a result of interruption of the blood supply to the area, as in coronary thrombosis. "A study showed that high expression of Lilrb2 was identified in patients with myocardial infarction, and downregulated Lilrb2 could visibly improve cardiomyocyte injury by regulating cell activity and apoptosis." (PMID 36704572, 2023). "We analyzed the expression levels of LILRB2, TLR2, NCF2, and S100A9 in AMI samples (blood samples on the first day of myocardial infarction) and stable coronary artery disease (CAD) controls." (PMID 34490057, 2021).
myopia (2 papers, 2024 to 2025). "Murine myopia models show elevated LILRB2/Pirb protein expression promotes fatty acid synthesis and lipid accumulation, disrupting choroidal function and accelerating pathological myopia progression." (PMID 41049435, 2025). "The increased protein expression of LILRB2/Pirb (mouse orthologous protein) in PM patients and myopia mouse models is validated." (PMID 39207058, 2024). "Considering that the LILRA3 protein was not expressed in mice eyes, we mainly investigated the relationship between LILRB2 and myopia in a mouse model." (PMID 39207058, 2024).
non-alcoholic steatohepatitis (2 papers, 2023 to 2025). "This may be explained by recent findings that LILRB2 activation is associated with macrophage recruitment and an inflammatory macrophage phenotype, as observed in non-alcoholic steatohepatitis (NASH)." (PMID 41030449, 2025).
pancreatic cancer (2 papers, 2017 to 2023). "In pancreatic cancer cell lines, an autocrine loop between LILRB2 and its ligand ANGPTL2 has also been demonstrated, leading to early stages of cancer, suggesting again a local action of ANGPTL2." (PMID 29138671, 2017). "The binding of ANGPTL2 to LILRB2 might be restricted to HSC, platelets, and some pancreatic cancer cells." (PMID 29138671, 2017).
sarcopenia (2 papers, 2022 to 2025). Progressive decline in muscle mass due to aging which results in decreased functional capacity of muscles. "They ultimately identified five candidate causal proteins associated with sarcopenia, including LILRB2, ASPN, CNTN2, ART4 and SOD2." (PMID 39949133, 2025). "We investigated the putatively potential causal effects of genetically predicted plasma protein levels on sarcopenia-related traits and identified three putatively causal proteins for ALM (LILRB2, ASPN, and CNTN2) and two for handgrip strength (ART4 and SOD2)." (PMID 35938019, 2022). "The direction of action is opposite to that obtained in this study, so the feasibility and the utility of LILRB2 to be a therapeutic target for sarcopenia may be relatively low." (PMID 35938019, 2022).
systemic lupus erythematosus (2 papers, 2016 to 2024). An autoimmune multi-organ disease typically associated with vasculopathy and autoantibody production. "Although the inhibitory receptor ILT4/LILRB2 has been related with the tolerogenic phenotype of DC, the possible role of this receptor in the breakdown of DC tolerogenic function in systemic lupus erythematosus (SLE) has not been elucidated." (PMID 27057555, 2016).
acute leukemia (1 paper, 2022). A clonal (malignant) hematopoietic disorder with an acute onset, affecting the bone marrow and the peripheral blood. "It has been shown that the suppression of CaMKs (CAMKIV) coupled with human leukocyte immunoglobulin-like receptor B2 (LILRB2) signaling is associated with decreased human acute leukemia proliferation in vitro and in vivo." (PMID 35159351, 2022).
brain tumor (1 paper, 2023). "LILRB2 expression in normal brain and GBM tissues was detected by immunohistochemistry, and the effect of LILRB2 on prognosis was evaluated in an orthotopic brain tumor model." (PMID 36853330, 2023).
bulimia nervosa (1 paper, 2022). A disorder characterized by recurrent episodes of binge-eating over which the individual feels a lack of control; these episodes of binge-eating are followed by recurrent compensatory behavior to prevent weight gain, usually self-induced vomiting. "Exposure to diesel exhaust was found to decrease plasma levels of LILRB2, a potentially protective factor against bulimia nervosa." (PMID 35602164, 2022).
cerebral malaria (1 paper, 2024). A sequestration of Plasmodium falciparum in the brain, which can cause coma and/or seizures. "The relation found between CXCL9 plasma levels, a chemokine implicated in Th1 response, CD8 T cells, and NK cell trafficking and recently reported for its implication in the pathogenesis of pediatric cerebral malaria, and LILRB2 revealed opposite immune mechanisms between D3 and D30." (PMID 38835780, 2024).
co-infection (1 paper, 2025). "Interestingly, both LILRB1 and LILRB2 were markedly upregulated in response to HCMV, especially after TB40 infection, with elevated expression already evident in TB40 single infection and further amplified during co-infection." (PMID 40980889, 2025).
cognitive decline (1 paper, 2024). "Our proposed model delineates how cognitive decline associated with aging and neurodegenerative diseases arises from the coordinated activation of specific immune receptors—PIRB/LILRB2 and C5aR2 in neurons, TLRs and CR3 in astrocytes, and TLRs and CR3 in microglia." (PMID 38299364, 2024).
ischemic stroke (1 paper, 2021). A stroke disorder caused by obstruction of blood flow to the brain, due to thrombotic (local blood clot formation) or embolic (due to a blood clot or other material traveling from another site) event. "Taken together, these data provide substantive evidence that NogoA expression on GFAP + reactive astrocytes contributes to the corralling of LILRB2 + infiltrating monocytes and macrophages in the primate brain post-ischemic stroke." (PMID 34824275, 2021).
lipid metabolism disorders (1 paper, 2024). "This study revealed the association between LILRB2 and PM, uncovering the molecular mechanism of lipid metabolism disorders leading to the pathogenesis of PM due to LILRB2 upregulation." (PMID 39207058, 2024).
liver cancer (1 paper, 2022). An epithelial or non-epithelial malignant neoplasm that arises from the liver. "Our results showed that LILRB2 and LILRB5 expression was positively associated with OS and DSS and that the mRNA expression of all LILRB family members was significantly positively correlated with RFS and PFS in liver cancer patients." (PMID 35321724, 2022). "Our previous study also discovered that LILRB2 in CD1c+ myeloid DC subsets was remarkably increased in PBMCs of HCC patients and the microenvironment of liver cancer." (PMID 35321724, 2022). "Our study revealed that the mRNA expression of LILRB1, LILRB2, LILRB3, and LILRB5 was downregulated, while compared with normal tissues, the mRNA expression of LILRB4 was upregulated in liver cancer tissues." (PMID 35321724, 2022).
liver inflammation (1 paper, 2024). "Our previous studies revealed that ANGPTL8 promoted high-fat diet-induced liver inflammation and fibrosis through the LILRB2/ERK pathway." (PMID 39019343, 2024).
oropharyngeal tumors (1 paper, 2020). "One of the epigenetically upregulated genes in these oropharyngeal tumors, the Leukocyte immunoglobulin-like receptor B2 (LILRB2), has been shown to be overexpressed and is a tumor promoting gene in HCC as well." (PMID 33133131, 2020).
osteoporosis (1 paper, 2021). A condition of reduced bone mass, with decreased cortical thickness and a decrease in the number and size of the trabeculae of cancellous bone (but normal chemical composition), resulting in increased fracture incidence. "A 5-gene combination (CCR1, CD33, HCK, LILRB2 and CYBB) was established as an optimal and effective biomarker for osteoporosis using SVM with feature selection and classification procedures." (PMID 34622712, 2021).
parasite infection (1 paper, 2022). "LILRB2 suppress immune cell activity and mainly reported in viral, bacterial and parasite infection." (PMID 34983375, 2022).
reovirus infection (1 paper, 2025). "In contrast, murine PirB promotes reovirus infection of nonsusceptible cells, but the human PirB homolog, LILRB2, does not." (PMID 39932305, 2025).
Salmonella Infections (1 paper, 2009). Infections with bacteria of the genus SALMONELLA. "To address this, we observed the effects of Salmonella infection on LILRB2 and LILRB4 expression." (PMID 19860908, 2009).
sarcoidosis (1 paper, 2022). Sarcoidosis is a multisystemic disorder of unknown cause characterized by the formation of immune granulomas in involved organs. "Furthermore, non-synonymous SNPs in LILRB2, GZMB, APOL1, CNN2, SWAP70, and CSF1R were shown in over 50% of sarcoidosis patients." (PMID 35860586, 2022).
Shock (1 paper, 2020). The state in which profound and widespread reduction of effective tissue perfusion leads first to reversible, and then if prolonged, to irreversible cellular injury. "It is also associated with FOSL2 in pediatric septic shock and LILRB2 and ITGAM in pediatric resolved SIRS." (PMID 32318053, 2020).
squamous cell carcinoma (1 paper, 2015). A carcinoma arising from squamous epithelial cells. "Intriguingly, LILRB2 was expressed in both adenocarcinoma and in squamous cell carcinoma samples (SFigure 1B)." (PMID 26056041, 2015).
systemic amyloidosis (1 paper, 2025). "Moreover, we identified strong interactions between transthyretin (TTR) oligomers—another well-characterized amyloid protein associated with systemic amyloidosis—and the LILRB2 and LILRB5 receptors." (PMID 41233352, 2025).
Takayasu arteritis (1 paper, 2024). A rare inflammatory large-vessel vasculitis primarily affecting the aorta and its major branches, but also other large vessels, causing stenosis, occlusion, or aneurysm. "Additionally, LILRA3 deletion with HLA-B*52 is significantly associated with Takayasu arteritis (TAK), characterized by inflammation of the aorta, suggesting that LILRA3-mediated blocking of the LILRB2-fibrin interaction may induce resistance to TAK." (PMID 39376567, 2024).
tuberculosis (1 paper, 2022). A chronic, recurrent infection caused by the bacterium Mycobacterium tuberculosis. "Because these cytokines perform anti-tuberculosis function, we conclude that LILRB2 is an attractive MDSC-related therapeutic target for tuberculosis control." (PMID 35757769, 2022).
viral infections (1 paper, 2022). "The lack of studies regarding LILRB2 but also LILRB1 polymorphisms in vertical transmission and viral infections makes it difficult to discuss the role of variants in this matter." (PMID 35877415, 2022).
vitiligo (1 paper, 2023). Generalized well circumscribed patches of leukoderma that are generally distributed over symmetric body locations and is due to autoimmune destruction of melanocytes. "Here we investigated the LILRB1 and LILRB2 association with vitiligo risk and evaluated the possible role of interactions between HLA-G and its receptors in this pathogenesis." (PMID 36831297, 2023). "We tested the association of the polymorphisms of HLA-G, LILRB1, and LILRB2 with vitiligo using logistic regression along with adjustment by ancestry." (PMID 36831297, 2023). "However, no study has evaluated the role of LILRB1 and LILRB2 polymorphisms in developing vitiligo or the possible interactions between HLA-G and the genes encoding its receptors." (PMID 36831297, 2023). "Accordingly, whether or not individual polymorphisms in HLA-G, LILRB1, and LILRB2 were associated with susceptibility to vitiligo and whether or not there were some epistatic interactions between them were, therefore, investigated here." (PMID 36831297, 2023). "Despite the latest advances in vitiligo, the role of the simultaneous genetic composition of HLA-G, LILRB1, and LILRB2 in disease development remains to be elucidated." (PMID 36831297, 2023).